TNF (tumor necrosis factor)
Diseases named in the same sentence as TNF in open-access papers (continued):
Sharing a sentence is not in itself a finding about the gene and the disease.
tumor (continued). "In support of this mechanism in response to tumour initiation, in vitro studies have shown that IL-1β, TNFα and IL-6 expression are induced by transformation with oncogenic forms of Ras in various human and mouse cell types." (PMID 32325966, 2020). "Macrophages (Mø) play different roles in tumor growth depending on their polarization to classically-activated macrophages (M1s, release tumor necrosis factor-alpha (TNF-α)) or alternatively-activated macrophages (M2s, release IL-10)." (PMID 32280302, 2020). "Major inflammatory stimuli in the tumor microenvironment such as tumor necrosis factor (TNF)-α, interleukin (IL)-1, and toll-like receptor (TLR) ligands released from dying cells during cancer treatment activate NF-κB in surviving cancer cells." (PMID 31936290, 2020). "Another possible reason is that the TNF-α decreased with tumor cells less resulted the activation of the immune system by thyroid carcinomaTherefore, more clincal studies and basic reseaches should be conducted in the future." (PMID 32819324, 2020). "Genetic ablation of other complement proteins such as C3 was also shown to have profound inhibitory effects on primary tumor growth and metastasis correlating to increased numbers of IFNγ+/TNFα+/IL10+ CD4+ and CD8+ T-cells." (PMID 33718121, 2020). "Several key cytokines, such as TNF-α and interleukin-1β (IL1β), stimulate inflammatory programs that coordinate functions of tumor-infiltrating leukocytes (TILs) and their presence in the tumor milieu via a plethora of proinflammatory chemokines." (PMID 33322099, 2020). "Tumor necrosis factor α (TNFα) and TGFβ signaling affect the tumor environment, tumor progression, and drug resistance." (PMID 32422889, 2020). "Cytokines such as IL-6 and TNF aid in tumor development by activating pro-survival signaling and anti-apoptotic pathways in cancer cells." (PMID 32523651, 2020). "One of the most studied signal molecules involved in expansion, invasion, and metastasization of tumor cells is Tumor Necrosis Factor-alpha (TNFα)." (PMID 32722560, 2020). "Th1 cells secrete interferon-γ (IFN-γ), Interleukin-2 (IL-2), and tumor necrosis factor (TNF-α) that result in an anti-cancer tumor immune microenvironment." (PMID 32370060, 2020). "It has been proved that TNF alpha (tumor necrosis factor alpha) and transcription factor NF-jB are the key factors that connect inflammation to tumor promotion." (PMID 33182840, 2020). "Eosinophils not only regulate T-cell activation but also exert anti-tumor responses through degranulation and secretion of granzyme A as well as TNF-α via their natural killer group 2 member D (NKG2D) binding to NKG2D ligands (NKG2DLs) on tumor cells." (PMID 32499786, 2020). "These cells produced inflammatory cytokines (such as TNF-α, interferon γ) and promoted the decay of vessel-intensive tumor." (PMID 35492191, 2020). "Activated CD8+ T cells secrete large amounts of inflammatory cytokines, such as tumor necrosis factor (TNF)-α and IL-6, and present a high cytotoxicity against tumor cells." (PMID 32708748, 2020). "Another approach has been to enhance the levels of TNF expressed by the tumor, by targeting parallel signaling pathways." (PMID 32053868, 2020). "Fruti treatment increased ROS, N-acetyl-β-D-glucosaminidase (NAG) and TNF-α levels in tumor tissue by 15, 29 and 79%, respectively, and reduced IL-10 by 68%, compared to vehicle group." (PMID 33020521, 2020). "The tumour microenvironment (TME) is a key driver of tumorigenesis and tumour-resident immune cells secrete pro-inflammatory mediators, such as macrophage-derived TNF-α, to downregulate PEDF and promote prostate tumour growth, angiogenesis, and metastasis." (PMID 33238558, 2020). "Mast cells produce TGF-β, CXCL8, and TNF-α, promoting epithelial-to-mesenchymal transition in tumor invasion and metastasis." (PMID 32023940, 2020).
tumor (continued). "Genetic deletion or pharmacological ablation of 5-LO or LTA4H significantly reduces the tumor burden in K-ras–driven pancreatic ductal adenocarcinoma and in xenograft mouse model of human pancreatic cancer, through reduction of TNF-α secretion." (PMID 32973519, 2020). "The chronic presence of TNFα in tumors strongly enhances tumor progression; in parallel, IL-6 is also considered a strong tumor-promoting factor." (PMID 33585241, 2020). "This was accompanied by increased expression of cytokines evaluated by flow cytometry, TNFα, and IFNβ in tumor cells and IL1β and IFNβ in macrophages, which can alter the TME and mediate off-target effects (bystander or abscopal effects)." (PMID 33202881, 2020). "Together these data show that focusing TNF activity selectively to endothelial cells is potentially safe and effective as tumor therapy." (PMID 31912630, 2020). "TAMs-specific TNFα or its receptors induce apoptosis in vitro and in vivo tumor model by activating CD8+ T cells." (PMID 32219066, 2020). "In the TME, tumour-derived TGF-β inhibits IFN-α, TNF-α, and IL-6 production in tumour-associated plasmacytoid dendritic cells (pDCs) to foster their immune tolerance functions." (PMID 33114183, 2020). "These cells produce various tumor-promoting cytokines, including TNF-α, IL10, and IL17A, and also the less well-studied cytokines such as IL21 and IL26." (PMID 31948053, 2020). "Our qPCR data demonstrated a drastic increase in TNFα transcription with a concomitant increase in fibrosis in tumor-bearing mice, which was reduced by WFA treatment." (PMID 32722688, 2020). "Other researchers have demonstrated that local administration of IL-2 increases the percentage of Th17 producing IFN-γ and TNF-α among tumor-infiltrating lymphocytes and induces the conversion of Tregs to Th17." (PMID 32148497, 2020). "The correct sentence should be: Tumor growth leads to the increased production of inflammatory cytokines and growth factors (mainly IL-1, IL-3, IL-6, IL-11, IL-23, and TNF-), and this perpetual process ensures immortality." (PMID 32293548, 2020). "This is postulated to happen through tumor microenvironment mediators such as TNF-α, vascular endothelial growth factor and epidermal growth factor." (PMID 33344090, 2020). "In the mouse skin carcinogenesis model, mice with deletion of tumor necrosis factor α (TNFα), a master pro-inflammatory cytokine, were refractory to development of either benign or malignant tumors, demonstrating the tumor-promoting role of inflammation." (PMID 32244522, 2020). "TNF-α is a pro-inflammatory cytokine and a pleiotropic factor, as it takes part in a wide range of functions, such as inflammatory responses, anti-tumor actions and homeostasis." (PMID 32443460, 2020). "Then, a biologically relevant number of hypoxic tumor cells undergo necrosis, and this sets off an inflammatory response in which leukocytes infiltrate the tumor area and produce cytokines such as tumor necrosis factor α and interleukin-1 or -6." (PMID 32630531, 2020). "Pro-inflammatory cytokines, including TNF-α, IL-1α, IL-1β, and IL-6, in the tumor microenvironment have been reported to promote tumor progression, metastasis, and invasion." (PMID 33348858, 2020). "TNF-α is known to promote PD-L1expression in cancer cells, which contributes to immune escape of tumor cells." (PMID 32984029, 2020). "Colorectal cancer mice receiving anti-TNF treatment in addition to double checkpoint blockade had an advantage in tumor rejection and survival compared to mice treated with double checkpoint blockade alone." (PMID 32486375, 2020). "Although TNFα was first identified as a tumor-suppressive cytokine, it has been shown to promote tumors through increased inflammation in CRC." (PMID 32317968, 2020).
tumor (continued). "The combination of miR-203 and miR-200c had the strongest inhibitory effect on the tumor sphere-forming ability of 16B/TNF cells." (PMID 31911577, 2020). "For example tumor necrosis factor α (TNF-α) exists either as a soluble or immobilized molecule in vivo, which was shown to define its role as selectively supporting or inhibiting tumor growth and survival in various tumor cell lines." (PMID 32637403, 2020). "Studies have proven that at high doses, TNF-α induces tumor cell apoptosis and stimulates anti-tumor immunity, while at low doses, it helps tumor growth, metastasis and the EMT, in both murine and human models." (PMID 33228048, 2020). "In this study, we evaluated the anticancer activity of Trichomicin in vivo, and found that it decreased the expression of IL-6 and TNFα in tumor tissues." (PMID 32317968, 2020). "TNF-α inducing cell death leaves a massive cell debris to the tumor microenvironment that can be recognized by macrophages and thus actuated the orientation toward M2 type." (PMID 33505964, 2020). "It is therefore expected that tumor cells would be able to use TNF-α and IL-6 signaling to their own advantage." (PMID 33178579, 2020). "Based on the cell death-promoting effect of TNFR1-complex II, the potency of human recombinant TNF-α as an anti-tumor therapy was tested in numerous clinical trials but declined owing to the unclear role of the TNFR1-mediated signaling pathway in cancer." (PMID 32929358, 2020). "This biphasic tumor response is characterized by an initial response that consists of T cell-independent TNFα-driven hemorrhagic necrosis of tumor, followed by a CD8+ T-cell-dependent control of residual disease." (PMID 32664564, 2020). "Nearly 70 and 40% of MT-901 tumor-bearing mice were rendered tumor-free following i.t. injections with dual cytokine loaded microspheres of IL-12/TNFα and IL-12/GM-CSF, respectively." (PMID 33178203, 2020). "In this regard, some approaches have used TNF-α administration to tumor tissue to induce cell death due to its necrotizing effects." (PMID 32883235, 2020). "GSEA also identified hallmarks of malignant tumours, including apoptosis, E2F targets, epithelial‐mesenchymal transition, TNF signalling via NF‐κB and angiogenesis." (PMID 32301283, 2020). "TNF-α activates NF-κB signaling, thereby contributing to inflammation, cell survival, proliferation, angiogenesis, tumor promotion, and metastasis." (PMID 32670264, 2020). "Outstandingly, high proportions of tumor‐infiltrating TNFα‐producing DCs, IFNα+ pDCs and IFNλ1+ cDC1s after TLR triggering were linked to a better clinical outcome." (PMID 33282290, 2020). "We propose that it is unlikely that the complex mixture of cues from the tumor microenvironment that instruct macrophages can be adequately targeted, and instead posit that the macrophage-intrinsic mechanisms that suppress TNF-α secretion should be studied." (PMID 33267818, 2020). "Pro-inflammatory cytokines such as IL-1β, IL-6 and TNF-α, secreted by microglia, have been shown to increase tumor invasiveness in vitro." (PMID 32765498, 2020). "TNF-α not only participates in fostering tumor growth through chronic inflammation but also amplifies apoptosis through activating the extrinsic pathway." (PMID 32823876, 2020). "Meanwhile, other studies have reported that TNF-α also has anti-tumor activity by destroying tumor vasculature and facilitating antitumor immune response." (PMID 33680949, 2020). "The strong positive correlations detected between serum PD-1, PD-L1, CTLA-4 and TNF-α levels also suggest a systemic immunosuppression in cats presenting these tumor subtypes." (PMID 32481540, 2020). "When these tumour cells were re‐challenged, they were as sensitive to TNF/Mel/SM treatment as the parental BN175 cells." (PMID 32419365, 2020). "Immunohistochemical expression of TNF-α was increased in tumor groups with high proliferation (p = 0.034)." (PMID 32156252, 2020).
tumor (continued). "Through its receptor (TNFR1), TNF-α plays a fundamental role in inflammatory, infectious, and tumor processes." (PMID 33029495, 2020). "By secretion of IFN-γ and TNF-α, which activate resident inflammatory cells and recruit other cytotoxic immune cells, NK cells induce tumor cell death." (PMID 33260925, 2020). "The release of these inflammatory molecules such as tumor necrosis factor (TNF) and specific cytokines can help mediate tumor apoptosis and control tumor cell proliferation." (PMID 33396862, 2020). "Taken together, these results suggested that tumor cell-derived TNF-α promotes the expression of IL-33 in CAFs via the TNFR2/NF-κB/IRF-1 pathway." (PMID 31659258, 2020). "These cytokines promote the recruitment of Tregs and myeloid-derived suppressor cells (MDSCs) in the tumor microenvironment and impair the production of IL-12 and TNF-α by LPS-stimulated DCs." (PMID 32054102, 2020). "TNF-α is an important inflammatory factor in the tumor microenvironment that is generated by tumor and stromal cells." (PMID 32120856, 2020). "During the process, those macrophages secrete TNFα and chemokines recruiting T cells, indicating that cGAMP-induced anti-tumor effect is involved with macrophages." (PMID 32887628, 2020). "We found a slight increase of tumor initiating cytokines such as TNFα, IL-17, and IL-13 in mP obese models, while a statistically significant increase in the more aggressive mT obese models." (PMID 32411709, 2020). "In this study, we only focused on the paracrine secretion of cytokines, mainly TNFα, by immune cells and their direct effects on the tumor cells." (PMID 33257690, 2020). "The most significantly enriched gene sets in primary tumours were epithelial mesenchymal transition (EMT), NFKB/TNF, TGF beta signalling, and gene sets associated with the loss of human stroma (inflammatory response and interferon response)." (PMID 32792481, 2020). "The authors found that antibiotics led to a decrease in efficiency of the tumor eradication due to a reduction in TNF production." (PMID 32582143, 2020). "Excessive TNF-α concentration in the tumor microenvironment shifts the balance towards invasion, resulting in a reduction in overall survival and disease-free survival." (PMID 32855976, 2020). "In vivo blockade of TNFα in mice bearing trastuzumab-resistant breast tumors inhibited tumor growth when trastuzumab was simultaneously administrated." (PMID 32391269, 2020). "The TIL CD8+ T cells showed strong cytotoxicity to J558 tumor cells, and produced TNF-α and IFN-γ upon co-culture with J558 tumor cells." (PMID 32292786, 2020). "The data highlight a novel and specific regulation of oncogenic factors by SMG7 and pinpoint a composite tumor suppressor role in response to TNF." (PMID 32602581, 2020). "Some studies have shown TNF-α to possess anti-tumor properties and can be exploited for treatment of some cancer types, while others have demonstrated it contributes to tumor progression by modulation of the immune response." (PMID 33123499, 2020). "To further elucidate the potential mechanism by which tumor cell-derived TNF-α promotes IL-33 expression in CAFs, we examined the expression of TNF-α receptors (TNFR1 and TNFR2) in both GC cells and CAFs." (PMID 31659258, 2020). "They adenovirally transduced the monocytes with an anti-CEA-CD64 CAR and documented reduced tumor progression in treated mice, accompanied by strong TNF secretion." (PMID 32429316, 2020). "Expression of anti-tumour cytokines, including TNFα, IL2, and IFNγ in sorted CD8+ cytotoxic cells, were measured by quantitative real-time PCR." (PMID 31913856, 2020). "It produces inflammatory cytokines such as TNF-alpha and IL-1 and provides a favorable microenvironment for tumor." (PMID 32933192, 2020).
tumor (continued). "Conditionally inactivated NF-κB in myeloid cells significantly reduced the expression of many inflammation-related genes, such as IL-1β, TNFα, human macrophage inflammatory protein, and cyclooxgenase 2, and tumor size significantly decreased in mice." (PMID 32317968, 2020). "We also determined the serum concentration of the common tumor-promoting cytokines (IL-6, VEGF, TGF-β, and TNF-α) using the enzyme-linked immunoassay (ELISA) in samples from the same patients with miRNA validation." (PMID 33125430, 2020). "The dependence of KC death on TNF signaling raises the possibility for the development of strategies aiming at enhancing tumor rejection." (PMID 33178579, 2020). "These tumor-promoting effects of TNFα in the TME are in contrast to its inhibition of breast cancer-cell proliferation by blocking the G1/S phase transition of the cell cycle." (PMID 32733461, 2020). "In some settings depending on the type of tumor, MCs can have an immunosuppressive role by releasing IL-10, histamine, and TNF-α." (PMID 31256327, 2020). "The presence of inflammatory cytokines such as IFN-γ and TNF in the tumour microenvironment is known to promote the recruitment of inflammatory immune cells, activate local immune cells, and promote tumour cell death." (PMID 33302918, 2020). "Here the selection pressure was the endogenous immune response, and not specific to CTLs, suggesting that autophagy protects tumors from various immune cells within the tumor microenvironment, most likely those with the ability to secrete TNF and IFN-γ." (PMID 33277468, 2020). "Tumour-associated macrophages (TAMs) produce TNF-α in a HPSE-dependent manner, driving inflammation and tumour growth." (PMID 33256730, 2020). "Chronic levels of TNF alpha production have been shown to promote DNA damage by reactive oxygen species (ROS), and support tumour growth through angiogenesis." (PMID 33137960, 2020). "SMs not only degrade IAPs to promote tumor cell death, but also induce the production of TNF in a subset of tumor cells, which can act in an autocrine or paracrine manner to cause tumor cell death." (PMID 31947615, 2020). "At the same time, inflammatory cytokine TNF-α has been reported to have vital roles in tumor progress as well as metastasis." (PMID 32194791, 2020). "SM and immune checkpoint blockade combination therapy was associated with increased expansion of CD8+ T cells, a decrease in Treg numbers and increased sensitivity of the tumours to TNF-induced cell death mediated through the RIPK1-Fadd-Caspase8 complex." (PMID 31947615, 2020). "By specifically targeting microglia, using propentofylline which blocks secretion of IL-1β, IL-6 and TNF-α, tumor growth was found to regress." (PMID 32765498, 2020). "Previous studies demonstrate that tumor-associated macrophages express high level of proinflammatory cytokines, such as TNF to promote tumor growth and invasion." (PMID 32171282, 2020). "Many authors demonstrated the anticancer effects of TNFα due to tumor cell proliferation inhibition, stimulating apoptosis, and increased cell differentiation." (PMID 33266223, 2020). "When promoting tumor growth, TNFα activates NF-κB and p38/MAPK pathways which stimulate signal transducer and activator of transcription 3 (STAT3), a known transcription factor classified as an oncogene." (PMID 32391269, 2020). "In fact, IL-34 expressed by osteosarcoma cells, is regulated by IL-1β and TNF-α, can also recruit macrophages into tumor tissues." (PMID 33224886, 2020). "The tumor source of TNF-α can be derived from myeloid or tumor cells and through autocrine activation can stimulate tumor growth and angiogenesis." (PMID 32283655, 2020). "For example, emodin can regulate a series of inflammatory cytokines, such as TNF-α, thereby reversing the immunosuppressive rates of tumor microenvironments and promoting tumor cell apoptosis." (PMID 32337232, 2020).